SNAPIN (SNAP associated protein)
Description:
Component of the BLOC-1 complex, a complex that is required for normal biogenesis of lysosome-related organelles (LRO), such as platelet dense granules and melanosomes. In concert with the AP-3 complex, the BLOC-1 complex is required to target membrane protein cargos into vesicles assembled at cell bodies for delivery into neurites and nerve terminals. The BLOC-1 complex, in association with SNARE proteins, is also proposed to be involved in neurite extension. Plays a role in intracellular vesicle trafficking and synaptic vesicle recycling. May modulate a step between vesicle priming, fusion and calcium-dependent neurotransmitter release through its ability to potentiate the interaction of synaptotagmin with the SNAREs and the plasma-membrane-associated protein SNAP25. Its phosphorylation state influences exocytotic protein interactions and may regulate synaptic vesicle exocytosis. May also have a role in the mechanisms of SNARE-mediated membrane fusion in non-neuronal cells. As part of the BORC complex may play a role in lysosomes movement and localization at the cell periphery. Associated with the cytosolic face of lysosomes, the BORC complex may recruit ARL8B and couple lysosomes to microtubule plus-end-directed kinesin motor.
Synonyms: BLOC1S7; SNAPAP; BORCS3; BLOS7; NEDBAC
Tractability: Antibody: UniProt places it where antibodies can reach, with medium confidence. PROTAC: ubiquitination databases record sites on it; its protein half-life has been measured.
Gene: Protein-coding gene on chromosome 1 (153,658,696 to 153,663,930, forward strand). Ensembl gene ENSG00000143553.
Subcellular location: Membrane; Cytoplasm, cytosol; Cytoplasm, perinuclear region; Golgi apparatus membrane; Lysosome membrane; Cytoplasmic vesicle, secretory vesicle, synaptic vesicle membrane
Subcellular location (Human Protein Atlas): Golgi apparatus; Nucleoli
Pathways (Reactome):
Vesicle-mediated transport: Golgi Associated Vesicle Biogenesis
Gene Ontology:
Molecular function: protein binding; SNARE binding; protein-macromolecule adaptor activity
Biological process: endosome to lysosome transport; lysosome localization; synaptic vesicle exocytosis; synaptic vesicle transport; anterograde axonal transport; anterograde synaptic vesicle transport; intracellular protein transport; lysosome organization; melanosome organization; neuron projection development; neurotransmitter secretion; organelle transport along microtubule; positive regulation of late endosome to lysosome transport; regulation of endosome size; regulation of lysosome size; insulin secretion; negative regulation of neuron projection development; regulation of synaptic vesicle exocytosis
Cellular component: BLOC-1 complex; BORC complex; perinuclear region of cytoplasm; synapse; synaptic vesicle; cytoplasmic side of lysosomal membrane; secretory granule; acrosomal vesicle; axon cytoplasm; cytoplasmic vesicle; cytosol; Golgi membrane; lysosomal membrane; manchette; membrane; microvesicle; synaptic vesicle membrane
Genetic constraint (gnomAD): Loss-of-function variants: 14 observed, 14.05 expected, observed/expected ratio (o/e) 1, 90% interval 0.66 to 1.55. The upper end of that interval is the gene's LOEUF score, 1.55, which puts it in group 6 of 6, group 1 being the genes least tolerant of losing a copy. Missense variants: 177 observed, 174.46 expected, observed/expected ratio (o/e) 1.01, 90% interval 0.9 to 1.15. Synonymous variants: 79 observed, 74.39 expected, observed/expected ratio (o/e) 1.06, 90% interval 0.88 to 1.28.
Homologues: Orthologues: macaque SNAPIN (99% identical), mouse Snapin (98% identical), pig SNAPIN (98% identical), dog SNAPIN (97% identical), guinea pig SNAPIN (97% identical), rabbit SNAPIN (96% identical), chimpanzee SNAPIN (90% identical), tropical clawed frog snapin (77% identical), zebrafish snapin (73% identical), rat Snapin (71% identical), Drosophila melanogaster Snapin (31% identical), Caenorhabditis elegans snpn-1 (24% identical).
Diseases named in the same sentence as SNAPIN in open-access papers:
SNAPIN is named in the same sentence as 10 diseases in open-access papers, as found by Europe PMC text mining. Sharing a sentence is not in itself a finding about the gene and the disease. The quoted sentences say what the papers report.
cognitive deficits (3 papers, 2022 to 2026). "Further studies are required to examine whether DYRK3-mediated phosphorylation of SNAPIN could reduce the synaptic production of Aβ, and attenuate the synapse loss and/or cognitive deficits seen in patients with AD." (PMID 36585413, 2022). "Future studies will be needed to determine whether CK1δ inhibition can reverse cognitive deficits in vivo and to explore whether this axis plays a broader role in other neurodegenerative or lysosomal storage disorders where SNAPIN function is compromised." (PMID 40791547, 2025).
viral infection (2 papers, 2025). "To investigate SNAPIN and virus-encoded protein interactions in the context of viral infection, we infected A549-Flag-SNAPIN cells with WSN." (PMID 41463543, 2025). "Studies in recent years have shown that SNAPIN can interact with viral proteins during viral infection, affecting virus replication and spread." (PMID 39859371, 2025).
Alzheimer disease (1 paper, 2022). A progressive, neurodegenerative disease characterized by loss of function and death of nerve cells in several areas of the brain leading to loss of cognitive function such as memory and language. "However, in the neurons of Alzheimer’s disease (AD) that are disturbed by amyloid β (Aβ) oligomers, SNAPIN reduces the interaction with dynein motors in the distal axon." (PMID 36585413, 2022).
diabetes (1 paper, 2021). "We also investigated SNAPIN expression by immunostaining, and diabetes mice had much less SNAPIN compared with WT controls." (PMID 34194388, 2021). "The function of SNAPIN in β cell growth is poorly understood, and our findings reveal that the overexpression of SNAPIN in Min6 cells can promote cell proliferation and is promising in achieving the goals of regenerative medicine for diabetes treatment." (PMID 34194388, 2021). "SNAPIN is mostly located in the cytoplasm, and to elucidate the role of SNAPIN in the development and progression of diabetes, a schematic outline of the immunoprecipitation mass spectrometry procedure was used in this study." (PMID 34194388, 2021). "SNAPIN expression increases with the age of mice and SNAPIN is down-regulated in diabetes." (PMID 34194388, 2021). "We can therefore try to design agonists for the SNAPIN sequence as a new treatment for diabetes." (PMID 34194388, 2021).
rheumatoid arthritis (1 paper, 2013). A chronic, systemic autoimmune disorder characterized by inflammation in the synovial membranes and articular surfaces. "Further, in rheumatoid arthritis (RA), Snapin (SNAP associated protein) was identified as a novel endogenous TLR-2 ligand." (PMID 23506673, 2013).
schizophrenia (1 paper, 2023). A major psychotic disorder characterized by abnormalities in the perception or expression of reality. "Among them, SNAPIN physically interacts with LAMA2 and is implicated in the pathophysiology of schizophrenia." (PMID 37511534, 2023).
infection (2 papers, 2025). The state of being infected such as from the introduction of a foreign agent such as serum, vaccine, antigenic substance or organism. "Our investigations revealed that the expression of SNAPIN was notably diminished following infection with various strains of IAVs both in vivo and in vitro." (PMID 39859371, 2025). "The quantitative PCR (qPCR) results demonstrated a marked reduction in the mRNA levels of SNAPIN 24 hpi following infection with the CK/C17-PB2/627K, WSN, and CK/C88 viruses." (PMID 39859371, 2025). "Consistent with this, overexpression of SNAPIN in A549 cells followed by WSN infection showed that SNAPIN suppresses viral replication." (PMID 41463543, 2025). "The results showed that the mRNA levels of SNAPIN were decreased at 24 hpi following infection with CK/C17-PB2/627K, WSN, and CK/C88." (PMID 39859371, 2025). "The results indicated that SNAPIN was downregulated following infection with IAVs both in vitro and in vivo, which is consistent with the proteomics results, suggesting that SNAPIN may serve as a key regulatory factor in the viral life cycle of IAVs." (PMID 39859371, 2025).
SNAPIN also shares sentences with these, for which no sentence is quoted: lysosomal storage disorders (2 papers); autism (1); ovarian carcinoma (1).